RN7SKP218 (RN7SK pseudogene 218)
Gene: Miscellaneous RNA gene on chromosome 7 (53,490,148 to 53,490,439, reverse strand). Ensembl gene ENSG00000222154.
Homologues: Orthologues: chimpanzee 7SK (86% identical). Paralogues in human: RN7SKP249 (67% identical), RN7SKP180 (67% identical), 7SK (67% identical), RN7SKP204 (66% identical), RN7SKP170 (66% identical), RN7SKP102 (66% identical), RN7SKP189 (66% identical), RN7SKP250 (66% identical), RN7SKP137 (65% identical), RN7SKP171 (65% identical), RN7SKP211 (65% identical), RN7SKP255 (65% identical), and 284 more.